JUN (Jun proto-oncogene, AP-1 transcription factor subunit)
Diseases named in the same sentence as JUN in open-access papers (continued):
Sharing a sentence is not in itself a finding about the gene and the disease.
cancer (continued). "In the pan-cancer FFLs, two genes, CCND1 and JUN, are drug targets of ATO." (PMID 26655252, 2016). "Pathway analysis of the 50 gene NIT signature revealed enrichment for MAPK signalling (DUSP1, JUN, NR4A1 and FOS), cancer specific (COX-2, PGE2, JUN and FOS), apoptosis induction (FOS and JUN) and genomic reformatting following (brain) ischaemia (EGR1 and JUN) pathways." (PMID 27384960, 2016). "In addition, the five genes (JUN, PRKACA, SMAD2, ESR1, and BCL3) shared by the OV and multi-NCA biomarkers form a small network module and are recognized as cancer-related genes." (PMID 26202601, 2015). "Here, we have used a network-based exploration approach to identify a multi-cancer gene expression biomarker highly connected by ESR1, PRKACA, LRP1, JUN and SMAD2 that can be predictive of clinical outcome in 12 types of cancer from The Cancer Genome Atlas (TCGA) repository." (PMID 26202601, 2015). "Given that our previous observation that the D150 residue of MELK is required for the interaction of MELK protein with the oncogenic transcriptional factors c-JUN and FOXM1 in a cancer-specific manner, it is likely that the kinase domain is essential for MELK-driven GSC survival." (PMID 24739874, 2014). "Moreover, many of them (such as MAPK, RHO, NOTCH, PDGF, RAS, JUN, ARF, PIK3) also belong to other cancer-related pathways." (PMID 22824167, 2012). "Such a set of hubs contained important transcription factors such as MYC and E2F1 and oncogenes such as JUN and RELA and was enriched with genes that appeared in cancer pathways (p<2.2×10−8), the cell cycle (p<3.5×10−6) and several important signaling pathways from DAVID." (PMID 21390271, 2011). "Furthermore, cancerous tissues exhibited higher c‐JUN expression compared to adjacent non‐cancerous tissues, suggesting that c‐JUN could serve as a potential therapeutic target for cancer treatment." (PMID 39976163, 2025). "Therefore, further investigation into the signaling pathways mediated by JUN/FOS and ITGB may offer new directions for developing pan-cancer precision therapies." (PMID 40725477, 2025). "JUN may indirectly promote the expression of TERT, activate telomerase activity, compensate for telomere shortening during cell division, maintain chromosomal stability, and assist in the unlimited proliferation of cancer cells." (PMID 40666524, 2025). "Additionally, c-JUN was found to regulate the expression of MMP1, a known mediator of cancer invasiveness, and MAP4K4, creating a feedback loop that may enhance metastatic potential." (PMID 39990663, 2025). "The upregulated DEGs showed various enforced transcription factors’ networks including IRF3, TAL1, JUN, and FOXA, whereas the downregulated DEGs demonstrated dramatic network suppression of E2F1, a cell cycle progressor, and NR2C2, a cancer-promoting orphan receptor." (PMID 37612293, 2023). "Interestingly, when we elevated the levels of FOSL1 and JUN simultaneously, the lung metastatic ability of cancer cells did not increase compared with cells that only had FOSL1 overexpression." (PMID 37395651, 2023). "Using qPCR assay for known genes modulated NT157 in other cancer models, we identified that NT157 decreased expression of oncogenes BCL2, CCND1, MYB, and MYC and increased genes related to cellular stress and apoptosis, JUN, BBC3, CDKN1A, CDKN1B, FOS, and EGR1 (all p < 0.05)." (PMID 36224313, 2022). "In addition, JUN, a putative transforming and remodeling gene, high expression of these molecules in CD4+ TILs might contribute the cells epigenome vulnerable to immunoediting with the cancer development." (PMID 33301062, 2021). "FRA1 binds to JUN to form heterodimeric AP-1 complexes, maintaining mesenchymal cell state, inducing EMT and generating CSCs from non-stem cancer cells." (PMID 37353480, 2023). "On the other hand, JUN, JUND, and FOSL1, another set of potential targets of HSF1 upregulated after heat shock, were expressed at higher levels (or not significantly changed) in all analyzed HSF1high cancers." (PMID 36010586, 2022).
cancer (continued). "FOS, JUN and MYBL2 are partly known to play a role in cancer, but not explicitly in MCL." (PMID 18416826, 2008).
infection (141 papers, 2006 to 2025). The state of being infected such as from the introduction of a foreign agent such as serum, vaccine, antigenic substance or organism. "During early-phase infection, there was robust upregulation of pro-inflammatory cytokines such as JUN, IL15, ATF2, TNFSF15, and CXCL10, indicating strong immune activation." (PMID 40649996, 2025). "For the cell host response in the early-phase infection, genes such as JUN, IL15, ATF2, TNFSF15, and CXCL10 were significantly upregulated, reflecting a strong pro-inflammatory and immune response." (PMID 40649996, 2025). "The THP-1 cells responded by upregulating the JUN transcription factor after infection with all the Aeromonas spp." (PMID 35874671, 2022). "Infection with P. aeruginosa upregulates several IEGs such as JUN, KLF2, and ZFP36 in epithelial cells." (PMID 35508983, 2022). "Transcript levels of JUN have been shown in numerous studies to increase in a variety of host cells after infection with T. gondii." (PMID 34781732, 2021). "The cells were previously pretreated with EP4 agonist, or JUN inhibitor, followed by infection and bacteria count at 2 and 24 hpi." (PMID 34319170, 2021). "DDIT3 can interact with FOS and JUN, hence its induction further suggests activation of apoptosis by infection." (PMID 31664929, 2019). "DDR1 expression in SW620 cells increased the transcript levels of MYC, FRA1, and JUN compared with control (mock infection)." (PMID 29438985, 2018). "In our analysis, genes coding JNK (MAPK8), c-Jun (JUN), and c-Fos (FOS) were all implicated in the subnetwork from the chronic stage of infection, and all showed significantly increased transcript expression levels at this stage." (PMID 28487699, 2017). "The expression of MAPK family genes, dual specificity phosphatases (DUSP) family members, TNF, IL-1, IL-6, JUN and NF-κB family genes were upregulated at early stage of infection in all the tissues indicated triggering of MAPK pathway." (PMID 28704394, 2017). "For example, siRNA studies to knock down JUN, the IAPs, or NF-κB expression will help to determine which changes are required for apoptosis inhibition upon infection." (PMID 20429941, 2010). "Infection with NH/P68 also caused down-regulation of IFNAR1 and NLRP3 receptors, MYD88 adaptor proteins, as well as other molecules involved in modulating receptor signaling pathways (JUN, PELI1, TBK1, and TICAM2)." (PMID 40530033, 2025). "Of particular interest, the expression of 6 genes (VSIG4, LAMP1, QPCT, C1QB, TNFSF13, and JUN) can be used to distinguish the transcriptomic signature of a dormant infection from an uninfected joint replacement highlighting the potential for these markers in diagnosing a dormant infection." (PMID 39563367, 2024). "Furthermore, in a ciliated cell line model, a very similar NF-kB-driven transcriptional signature (including NFKBIA, FOS and JUN) has been shown to be specifically induced in SARS-CoV-2-infected cells immediately (< 3 h) post-infection." (PMID 37700317, 2023). "TP63, FOXA1, STAT1, ELK1, FOS, and JUN are TFs in various lung injury or infection types." (PMID 36911695, 2023). "Thus, infection with H. pylori wt bacteria triggers a quick response of the host that results in activation of transcription factor genes JUN and NFKB1." (PMID 37193047, 2022). "The transcription of JUN was unaffected between both cell types following infection." (PMID 35746681, 2022). "Notably, JUN was activated in mock-infected cells and maintained throughout early infection (6 h), but repressed as the infection progressed (16 h)." (PMID 28993767, 2017). "The expression profile of JUN stands out as its transcriptional profile suggests transcriptional activation at later infection times and its similar response in the three datasets suggests that this gene might be a marker that induces apoptosis in infected cells." (PMID 36435849, 2022).
infection (continued). "Interestingly JUN (c-JUN; AP-1, P05412) was highly upregulated in response to YopJC172A Y. pseudotuberculosis in comparison to wild-type infection (fold change, FC = 23), indicating a potential role for this transcriptional factor in mediating the host response to LPS and specific effects on PGE2." (PMID 34319170, 2021). "In addition, FOS and JUN were downregulated at this time point post-infection." (PMID 22455317, 2012). "Components of the JNK and p38 MAPK pathway were induced upon early infection, including the c-Jun N-terminal kinase (JNK) gene MAPK10 as well as the transcription factor AP-1 components FOS, JUN and JUNB." (PMID 38427950, 2024). "Here, we found that both colonic and ileal networks generated with CARNIVAL shared similar transcription factors, including ATF2/3, FOS, JUN, STAT1, and NFKB1, which were all upregulated in both tissues upon infection." (PMID 35501398, 2022). "Among the proteins that were most robustly upregulated in cells infected with YopJC172A-expressing Y. pseudotuberculosis in comparison to wild-type infection, NDRG1 (Q92597) was one of the top hits (FC = 35), followed by JUN (P05412, FC = 23)." (PMID 34319170, 2021). "Whereas the signaling pathways enriched in subtype S2 primarily regulated the MAPK signaling pathway and osteoclast differentiation, as well as the infection of virus and E. coli bacteria, targeting the down-regulated TFs, such as NFKB1, FOS, and JUN." (PMID 33777111, 2021). "Specifically in the module, we find genes induced in response to infection such as IL1B, TNF, IL6, IL12B, NFKBIA, JUN, and MAP3K8, which are related to Toll-like receptor signalling (Appendix B)." (PMID 33498280, 2021). "Our systems biology analysis revealed that 13 hub genes, including the classical inflammatory genes (IL6, NFKB2, JUN, IL-1β, and CXCL2) which regulate retinal innate responses during infection." (PMID 26865111, 2016). "The systems biology analysis identified multiple immune system and inflammation molecules (e.g., STAT3, STAT1, CEBPB, JUN, IGF1, SPP1, NFKB2, IL-1β, and CSF1) as master regulators that are activated upon infection." (PMID 26865111, 2016). "Toward this we knocked down some important transcriptional regulators such as CREB, c-JUN, and SOX-5 in macrophages prior to infection with MTB." (PMID 26697414, 2015). "In contrast, there was a greater activation of genes such as TNF-α, IL1A, IL8, JUN, ERRFI1 and KLF6 after infection with N. lactamica relative to N. meningitidis." (PMID 22028815, 2011). "In summary, these results demonstrated progressive activation of the JNK-c-JUN pathway in HCoV-229E-infected cells within 24 h of infection, but not in non-infected bystander cells." (PMID 40968155, 2025). "This was supported by the upregulation of the NF-kB inhibitor genes NFKBIA and NFKBIZ, the AP-1 transcription factor complex genes FOS, JUN, FOSB and JUNB as well as other NF-kB target genes such as TNFAIP3, RELB, NR4A2, DUSP1 and CD69 in response to infection." (PMID 37700317, 2023). "Three promising genes (EGR1, JUN and FOS) were eventually identified, and were significantly and differentially expressed in the same breed under different conditions, and in the two breeds after ST infection." (PMID 36557693, 2022). "Clear host transcriptional responses could be observed 8 h after infection, including the documented MAPK-based activation of FOS, EGR1, and c-JUN gene expression, in both parental and uS10-KI cells." (PMID 33912921, 2021). "Moreover, several TFs, such as NFKB1, p65, JUN, SP1 and STAT3, were demonstrated previously to be involved in the regulation of lung inflammation and immunity during pathogen infection or external stimulation." (PMID 32592597, 2020). "Furthermore, our results demonstrate that infection of THP-1 macrophages with R. conorii resulted in the increased abundance of transcripts of different members of the AP-1 complex such as FOS, JUN, and JUNB." (PMID 31024862, 2019).
infection (continued). "In the same study, infection of moMΦ with Georgia 2007 strain down-regulated other receptors, such as interferon receptors (IFNAR1, IFNAR2, IFNGR) and interleukin receptors (IL4R, IL10RA, IL10RB, and IL17RA), as well as transcriptomic factors (e.g., FOS, JUN, and TBK1)." (PMID 40530033, 2025). "Compared with infection with the WT strain, infection with the LLM deletion strain significantly reduced the mRNA expression of nuclear factor kappa B subunit 1 (NFKB1) (3.37-fold, p < 0.001) and AP1 or JUN (3.42-fold, p < 0.001) in the NF-κB and MAPK/AP-1pro-inflammatory signaling pathways." (PMID 40076391, 2025). "Of the 227 BRD4 interactors that were recruited to the BRD4 complex during RSV-infection, we observe that 95 ( 42%) are disrupted to some degree by treatment with ZL0454, including most of the transcription factors described in the earlier section (e.g., c-JUN, CTNNB1, JUP, DDX3X, MTDH)." (PMID 33799525, 2021). "Also the expression of transcription factors was significantly modified by HHV-6A/6B infection, with an early increase of ATF3, JUN and FOXA2 by both species, whereas HHV-6A specifically induced a 15-fold decrease of POU2AF1, and HHV-6B an increase of FOXO1 and a decrease of ESR1." (PMID 29163428, 2017).
neurodegenerative disease (15 papers, 2013 to 2026). A disorder of the central nervous system characterized by gradual and progressive loss of neural tissue and neurologic function. "Notably, JUN (encoding for c-Jun) is upregulated in neurodegenerative diseases, including AD32,36." (PMID 38049398, 2023). "Previous studies have described the up-regulation of certain genes involved in neurodegenerative diseases including amyloid precursor protein (APP), ubiquilins (UBQLN) and Jun proto-oncogene (JUN) as candidate genes for NAFLD." (PMID 34565410, 2021).
bacterial infection (8 papers, 2015 to 2025). "The genes MAPK12 and JUN were related to the bacterial infection and to the toll-like receptor signaling pathway BP." (PMID 34504189, 2021). "These were predominantly enriched in the Toll-like receptor signaling pathway and bacterial infection-related genes, such as TLR4, JUN, and TNFSF10." (PMID 41375527, 2025).
neurological disorders (8 papers, 2007 to 2025). "Moreover, supporting RFX7’s potential role in neuronal development and neurological disorders, we identified regulators of neuronal processes among the novel RFX7 targets, such as JUN, SYNPO, PPP3CA, and PPP2R5D." (PMID 36864036, 2023).
renal disease (6 papers, 2020 to 2025). "Finally, the Nephroseq V5 tool was applied to identify the expression level of CCL2, FOS, JUN in kidney diseases, as well as the correlation between CCL2, FOS, JUN expression and renal function in the patients with IgAN." (PMID 35464092, 2022).
hematologic disorder (3 papers, 2018 to 2025). A disease involving the hematopoietic system. "FOS and JUN are transcription factors in the AP-1 family, regulating the oncogenesis of multiple types of lymphomas, and GATA1 is essential for hematopoiesis, the dysregulation implicated in multiple hematologic disorders, and malignancies." (PMID 36810839, 2023).
immune disorders (3 papers, 2021 to 2025). "Transcriptional activation of JUN is also a hallmark of immune aging, contributing to inflammaging, which could influence HIV-related immune dysfunction." (PMID 40574839, 2025). "While some of these regulatory factors (e.g., NFKB, STAT, and IFN) have been reported as shared TFs enriched in inflammatory fibroblasts across a diverse group of immune disorders, others displayed distinctive TFs (e.g., FOSL2, JUN, and ELK4) unique to inflammatory keratocytes." (PMID 39677756, 2024).
cardiovascular disease (2 papers, 2016 to 2022). "We constructed an mRNA–miRNA–lincRNA ceRNA interaction network centered on miR-22-3p and used the starBase v2.0 and miRWalk databases to predict eight related transcription factors associated with cardiovascular disease, namely, CTCF, JUN, JUND, NFATC1, NFE2L2, RAD21, RELA, and TAL1." (PMID 36105099, 2022).
gynecological diseases (1 paper, 2013). "CAPS3, JUN and FOS were targeted by all the 27 formulae, which probably explain the common mechanism of the 27 formulae having same or similar therapeutic effects as SWT on gynecological diseases." (PMID 24223693, 2013).
peripheral nerve disease (1 paper, 2022). "The expression of the c-JUN gene increases rapidly after nerve injury and in peripheral nerve disease, and it has a critical role in axon regeneration." (PMID 36970310, 2022).
vasculopathy (1 paper, 2024). "Moreover, the top downregulated genes included several immediate early transcription factors related to angiogenesis and vasculopathy, such as JUN (log2FC −1.76, adj." (PMID 38791244, 2024).
JUN also shares sentences with these, for which no sentence is quoted: esophageal squamous cell carcinoma (10 papers); peripheral neuropathy (10); renal carcinoma (9); acute lymphoblastic leukemia (8); ischemia (8); anaplastic large cell lymphoma (7); Parkinson disease (7); colorectal tumors (6); Hepatic steatosis (6); hepatitis C virus infection (6); inflammatory bowel disease (6); lymph node metastasis (6); intestinal cancer (5); multiple myeloma (5); myeloid leukemia (5); skin inflammation (5); Anxiety (4); Cognitive impairment (4); endothelial dysfunction (4); Myocardial fibrosis (4); non-alcoholic steatohepatitis (4); steatosis (4); adenocarcinoma (3); amyotrophic lateral sclerosis (3); cerebral infarction (3); colorectal adenoma (3); fibrosarcoma (3); Herpes simplex infection (3); hypopharyngeal carcinoma (3); inflammation (3).
A further 248 diseases each share a sentence with JUN in 3 papers or fewer.